RHOA (ras homolog family member A)
Diseases named in the same sentence as RHOA in open-access papers (continued):
Sharing a sentence is not in itself a finding about the gene and the disease.
breast carcinoma (continued). "Besides, non-invasive MCF-7 breast cancer cells with transiently suppressed RhoA expression exhibit an increased invasiveness (RhoA-: 183.1 ± 23.45% vs. control; P < 0.05; n = 9)." (PMID 33087801, 2020). "In addition, the overexpression of miR-146a reduced the capacity of breast cancer cells to migrate and invade owing to the downregulation of RhoA." (PMID 33396906, 2020). "Some studies show potential tumor and metastasis suppressive ability of RhoA in breast cancer." (PMID 32443784, 2020). "In addition to an anti-invasive and tumor-suppressive function, RhoA also has a pro-invasive role in breast cancer." (PMID 33291460, 2020). "A study of Rho proteins in basal-like breast cancer showed a luminal cell line derivative acquired basal characteristics while simultaneously increasing expression of RhoA protein: inhibition of RhoA by RNA interference decreased cellular migration and invasion." (PMID 33162807, 2020). "All together, these studies suggest contradicting effects, and may point to a more context-dependent role for RhoA on breast cancer motility and invasion." (PMID 32992837, 2020). "Therefore, our study suggests that RhoA suppresses breast cancer cell metastatic dissemination by suppressing the invasiveness of tumor cells through reduced expression of the tumor CXCR4 receptor with a subsequent reduction of CAFs in the TME." (PMID 31705019, 2019). "Role of RhoA in breast cancer tumorigenesis and tumor progression have long been a topic of debate." (PMID 31705019, 2019). "On the other hand, Y16, which also prevents the binding between RhoA and its GEF enzymes by binding between the DH and PH domains of Leukemia-associated RhoGEF (LARG), suppresses breast cancer proliferation, migration and invasion, as well as modifies the distribution of the actin cytoskeleton." (PMID 30884855, 2019). "Indeed, in breast cancer cells, RhoA activity at cell–cell contact is regulated by p190B through a complex with p120-catenin." (PMID 31013840, 2019). "Interestingly, Rack1 also interacts with Rho and activates RhoA/Rho kinase pathway to enhance breast cancer metastasis." (PMID 31113450, 2019). "Wnt5a also induced ROR1-dependent tyrosine phosphorylation of cortactin (Y421), which recruited ARHGEF1 to activate RhoA and promote breast-cancer-cell migration; such effects could be inhibited by cirmtuzumab, a humanized mAb specific for ROR1." (PMID 31667337, 2019). "The effects of altered RhoA expression on breast cancer invasion in vitro raises the possibility that RhoA may have a causal role in suppressing breast cancer cells metastasis." (PMID 31705019, 2019). "RHOA is the target of miR-146a to prevent cell invasion and metastasis in breast cancer." (PMID 30930932, 2019). "Furthermore, macrophage contacts with breast cancer cells have been shown to induce RhoA GTPase signalling within the cancer cells and to trigger their intravasation." (PMID 31313988, 2019). "We found that when we inhibited RhoA activation, human breast cancer cells could form channels more easily." (PMID 30814488, 2019). "How do macrophages upregulate RhoA GTPase activity within breast cancer cells?" (PMID 31313988, 2019). "In this regard, we found that cirmtuzumab could block the capacity of Wnt5a to induce ROR1 to complex and phosphorylate cortactin, recruit ARHGEF1, and activate RhoA, thereby suppressing breast-cancer-cell migration/metastasis." (PMID 31667337, 2019). "Collectively, these findings strongly suggested that the mouse 4T1 breast cancer cells could be used to investigate the role of RhoA in metastasis." (PMID 31705019, 2019). "Indeed, in breast cancer cell lines, ectopic expression of p190A induced cell death in a RhoA and caspase-dependent manner." (PMID 31013840, 2019). "The role of RhoA GTPases in breast cancer tumorigenesis and metastasis is unclear." (PMID 31705019, 2019). "Together, these results suggested that in breast cancer cells, RhoA suppresses cell invasiveness." (PMID 31705019, 2019).
breast carcinoma (continued). "The miRNA miR-31 suppresses breast cancer cell metastasis by targeting genes such as RhoA." (PMID 31248165, 2019). "Interferon regulatory factor 4 binding protein (IBP, a Rho-family guanine nucleotide exchange factor for Rho family GTPases, including Rac1, RhoA and Cdc42) can mediate Rac1, RhoA and Cdc42 activation in breast cancer cells to regulate actin cytoskeleton rearrangement and MMP production." (PMID 30754684, 2019). "In a recent in vitro study performed in breast cancer cells, we showed that RSU-1 silencing downregulates several actin-modulating genes, namely PARVA, RhoA, Rho associated kinase-1 (ROCK) and Fascin-1 and leads to inhibition of breast cancer cell migration and invasion." (PMID 31412547, 2019). "Collectively, these findings suggested that RhoA could act as a physiological suppressor of breast cancer lung metastasis in mice." (PMID 31705019, 2019). "For tamoxifen-resistant MCF-7 cells, one proteome report demonstrated that tamoxifen-resistant breast cancer cells are characterized by downregulated ER signaling, the activation of alternative survival pathways, and enhanced cell motility, including RhoA protein." (PMID 29743060, 2018). "The results showed that this stratification approach using MMP-9/RhoA biomarker-combination might be useful for early breast cancer diagnostics, although the authors admitted the existence of limitations in the stratification system." (PMID 30262739, 2018). "AC inhibited the mRNA expression of RhoA in both the breast cancer cells." (PMID 29743060, 2018). "Moreover, AC can inhibit the mRNA expression of RhoA, the upregulated protein in tamoxifen-resistant breast cancer cells, in both the ER-positive and tamoxifen-resistant breast cancer cells." (PMID 29743060, 2018). "The idea that aberrant RhoA activation drives breast cancer metastasis fits with the findings of others indicating that reduced expression of the RhoA subfamily-specific GAP DLC-1 is predictive of metastatic spread to the bone in all breast cancer subtypes." (PMID 29769144, 2018). "Furthermore, qPCR showed that the mRNA expression of Skp2 and downstream genes, RhoA, was inhibited by treatment of both ER-positive and tamoxifen-resistant breast cancer cells with AC." (PMID 29743060, 2018). "The anti-tumor effect following cytofectin-mediated delivery of anti-RhoA and anti-RhoC siRNAs was evaluated in a breast cancer mouse model, developed by employing 4 × 106 of MDA-MB-231 cells (human breast carcinoma cells) into female athymic nude mice of 6 weeks of age." (PMID 29861465, 2018). "Indeed, CES1 silencing or ICMT overexpression increased RhoA activity and prompted strong changes in cytoskeletal organization in breast cancer cells." (PMID 28729673, 2017). "Moreover, ectopic expression of a gain-of-function mutant RhoA (V14) rescued breast cancer cells from migration-related defects." (PMID 28085666, 2017). "Despite other studies also suggesting Asc may be involved in regulating breast cancer cell proliferation and migration through Akt and RhoA, respectively, it is unclear whether Asc/TETA is effective through the same pathways and warrants further investigation." (PMID 28280522, 2017). "In addition, Annexin-A1 increases breast cancer invasion by activating RhoA in an ERK-dependent fashion." (PMID 27391444, 2016). "We next examined whether endogenous RhoA and ERK interact with each other and whether this association also exists in breast cancer cell lines." (PMID 26816343, 2016). "For example, miR-31 is significantly decreased in breast cancer and could exert a tumor suppressor function in breast cancer by inhibiting RHOA." (PMID 26885612, 2016). "Thus, RhoA can reverse the inhibition effect on cell metastasis by NRF2 downregulation in breast cancer cells." (PMID 27713154, 2016).
breast carcinoma (continued). "In this non-Smad pathway, TGF β RII phosphorylates PAR6 (partitioning-defective protein 6), then inactivates the epithelial polarity complex, as well as activating of the small GTPase RhoA, which is contribute to cell invasion leading to breast cancer metastasis." (PMID 26932781, 2016). "In addition, we have also shown that ANXA1 can enhance ERK activity and RhoA activity in breast cancer." (PMID 27105503, 2016). "Taken together, these data demonstrated that NRF2 could activate downstream signal transduction of RhoA, leading to increased formation of stress fiber and focal adhesion, which further influences breast cancer cell metastasis." (PMID 27713154, 2016). "Moreover, RhoA is both overexpressed and spontaneously active in the invasive breast cancer cell line MDA-MB-231." (PMID 26816343, 2016). "Thus, we postulated that cytoskeletal rearrangement induced by deregulation of RhoA/ROCK pathway is a critical step in breast cancer progression." (PMID 27203208, 2016). "Here we demonstrate that recovery of RhoA expression in NRF2-silenced breast cancer cells could rescue NRF2 depletion-induced cell proliferation and metastasis decrease in vitro." (PMID 27713154, 2016). "Finally, in breast cancer cells it was demonstrated that overexpression of miR-31 decreases invasion and metastasis via downregulation of RHOA." (PMID 25883651, 2015). "A number of studies have shown that RhoA had abilities to control cancer metastasis and progression and the expression of RhoA was up-regulated in several common malignancies including gastric, pancreatic and breast cancer." (PMID 26066055, 2015). "Moreover, other studies demonstrated that silencing RhoA leads to the inhibition of cellular invasion, particularly in breast cancer cell lines." (PMID 24627003, 2014). "Knowing that Rac1 plays a major role in breast cancer motility and adhesion formation and knowing the antagonistic effect of RhoA and Rac, we started by looking at the dynamics of cellular adhesion directly following Rac and RhoA knockdowns." (PMID 24627003, 2014). "In breast cancer cells, RhoA activity as detected by RhoA-GTP was inhibited by GGTI-298." (PMID 23607551, 2013). "RhoA, RhoB and Cdc42 protein expression was detected in all breast cancer cases." (PMID 23420497, 2013). "Future studies will determine whether any of these molecules contribute to the suppression of RhoA by BCAR3 and, in so doing, help to elucidate the mechanism by which BCAR3 affects the balance between Rac1 and RhoA signaling in invasive breast cancer cells." (PMID 23762409, 2013). "The aim of this study was to examine the expression of ERM (ezrin, moesin) and Rho (RhoA, RhoB and Cdc42) proteins in breast cancer (BC) patients and to investigate the relationship between the sub-cellular localisation of these proteins and clinicopathological characteristics and patient survival." (PMID 23420497, 2013). "Similarly, we chose RHOA, MKI67, CITED2, ACTA2, FN1 and TGFB3, as all have been implicated in EMT and highly metastatic breast cancer." (PMID 23441166, 2013). "Although not mutually exclusive, a second possibility that may account for the BCAR3-dependent Rac1 activity observed in invasive breast cancer cells is that BCAR3 may actively suppress RhoA signaling, leading indirectly to Rac1 activation." (PMID 23762409, 2013). "Additionally, miR-155 can promote tumor invasion and metastasis in breast cancer by downregulating its target, RhoA and promote tumor invasion and metastasis in pancreas duct carcinoma by repressing the expression of TP53INP1." (PMID 21533124, 2011). "Furthermore, we confirmed that RRIG1 was able to suppress RhoA activity, whereas antisense RRIG1 promoted RhoA activity in these breast cancer cells." (PMID 21266059, 2011).
breast carcinoma (continued). "Furthermore, stimulation of endogenous G12 signaling by thrombin, which activates the G12-coupled protease-activated receptor (PAR-1), led to JNK and c-Jun activation in breast cancer cells in a manner that was inhibited by expression of DN RhoA." (PMID 22087220, 2011). "Indeed, estrogen has been found to activate RhoA and this activity is necessary for cytoskeletal remodelling and for the enhancement of breast cancer cell migration and invasion." (PMID 21838876, 2011). "The interaction of CD44 and HA activates RhoA signals and Rho kinase, enhances serine/threonine phosphorylation on Gab-1 (Grb2-associated binder-1), induces PI3K activation, triggers the PI3K/Akt pathway, and is involved in the progression of breast cancer." (PMID 21294926, 2011). "Rho GTPases including RhoA, Rac1, and Cdc42 are elevated and hyperactivated in breast cancer." (PMID 20860838, 2010). "RhoA, Rac1, Cdc42, and other family members are overexpressed and hyperactivated in early and late stage human breast tumors, and elevated RhoA and Rac1 expression correlates with breast cancer progression." (PMID 20860838, 2010). "In the present study, we thus attempted to analyse whether the impairment of Ras and/or RhoA prenylation could be a potential mechanism by which ZOL mediated its anti-invasive effect on the aggressive MDA-MB-231 breast cancer cell line." (PMID 12771933, 2003). "Additionally, CXCR4 may link to G12/13, promoting metastasis in basal‐like breast cancer cells in a RhoA‐dependent manner." (PMID 40969301, 2025). "In addition, CAF-derived IGF-1 stimulates tumour cell invasion and lung metastasis in orthotopic models of breast cancer through activation of the RhoA/ROCK/p-MLC pathway and TAM-derived IGFs promotes cancer cell-stemness and invasiveness in in vitro models of thyroid cancer." (PMID 39165364, 2024). "RhoA signaling was consistently elevated in metastatic vs primary breast cancer, and in HER2-enriched, luminal A and luminal B subtypes, and may therefore be prioritized for therapy in combination with inhibitors of subtype-specific S-drivers to prevent metastatic disease." (PMID 37463901, 2023). "However, the mechanism of this difference remains unclear and may be due to differences in tumor type, sample size, and statistical methods.PTK6 regulates RhoA and Ras via phosphorylation of p190 to promote the growth, migration and invasion of breast cancer." (PMID 37932734, 2023). "Thus, we can speculate that GBK inhibits the migration and invasion of breast cancer cells by promoting the expression of miR-31, which in turn impaires the expression of miR-31 target genes, such as RHOA, WAVE3, and SATB2." (PMID 36313626, 2022). "Together with data from our prior report, these findings suggest that mechanotaxis is a response shared by prostate and breast cancer cells but that profound differences in how force sensing is translated are dictated by cell intrinsic determinants that include adhesion interactions and RhoA‐ROCK." (PMID 35520391, 2022). "In addition, we determined that MEX3A could activate RhoA/ROCK1/LIMK1 signaling in the breast cancer cells." (PMID 34486491, 2021). "Therefore, we speculate that MEX3A promotes the progression of breast cancer through RhoA/ROCK1/LIMK signaling pathway." (PMID 34486491, 2021). "In addition, we investigated whether RhoA and RhoC expression contributes to poor prognosis in patients with breast cancer." (PMID 33406809, 2021). "Furthermore, MEX3A can regulate RhoA/ROCK1/LIMK signaling pathway in breast cancer cells." (PMID 34486491, 2021). "Concurring with the role of RhoA in cytoskeletal regulation, it is important for the progression and metastasis of different human tumors including liver cancer and testicular cancer, colorectal cancer, hepatocellular carcinoma, osteosarcoma, and breast cancer cells." (PMID 33546351, 2021). "Therefore, we investigated whether MEX3A affected RhoA/ROCK1/LIMK1 signaling in breast cancer cells." (PMID 34486491, 2021).
breast carcinoma (continued). "Therefore, MEX3A modulates the activity of RhoA/ROCK1 signaling in breast cancer." (PMID 34486491, 2021). "In addition, RhoA was reported to be a direct target of HIF1A in breast cancer cells." (PMID 33875796, 2021). "Furthermore, we found that mesenchymal transformed breast cancer cells treated with a Rho activator exhibit a decreased invasive capacity (RhoA activator II: 22.99 ± 9.922% vs. untreated; P = 0.0401; n = 7), which could be verified for TNBC cells as well." (PMID 33087801, 2020). "Therefore, we could conclude that Smurf1 facilitates breast cancer cell migration in a RhoA-dependent manner." (PMID 33718111, 2020). "Therefore, it is essential whether diosgenin could decrease the expression of RhoA and stabilize Twist level due to Skp2 downregulation in breast cancer cells." (PMID 32626765, 2020). "Consequently, IBP may regulate EMT and the movement of breast cancer cells via Rac1, RhoA and Cdc42 signaling pathways." (PMID 30754684, 2019). "In addition, FAM53A may affect the migration and invasion of breast cancer cells by regulating the expression of RhoA, RhoB, RhoC, ROCK1, and MMP9." (PMID 31799197, 2019). "The data indicate that RhoC may be more important for breast cancer development compared to RhoA." (PMID 29152087, 2017). "Interestingly, Memo1 has been linked to NADPH oxidase activity in breast cancer cells, however the exact mechanism underlying these results, as well as a role for RhoA, has not been established and is likely to be context-dependent." (PMID 28085666, 2017). "Indeed, it has been reported that RACK1 may play a role in the promotion of breast cancer cell migration, by binding to and activating RHOA." (PMID 28686225, 2017). "In addition, ANXA1 can enhance ERK and RhoA activity in breast cancer cells." (PMID 29263330, 2017). "Additional studies in melanoma and breast cancer, which are strongly influenced by RhoA/C pathways, as well as identification of the properties of tumor subsets that might make them particularly responsive to this family of compounds will be important future directions." (PMID 27600078, 2016). "Combined with our findings that NRF2 modulation more greatly affected MDA-MB-231 cells, which exhibit higher RhoA expression, we inferred that RhoA may be a key factor in the NRF2 deficiency-mediated inhibition of breast cancer cell proliferation and metastasis." (PMID 27713154, 2016). "This may enhance RhoA protein stability and lead to RhoA overexpression in breast cancer cell." (PMID 27713154, 2016). "In this study, we investigated the expression of the ERM (ezrin, moesin) and Rho (RhoA, RhoB, Cdc42) protein families in a homogeneous group of patients with stage II invasive ductal breast cancer (BC)." (PMID 23420497, 2013). "We next examined whether RhoA was downstream of Dvl2 in human breast cancer cells." (PMID 22655072, 2012). "Then, we examined whether Daam1 could activate RhoA in other human breast cancer cells." (PMID 22655072, 2012). "Thus, down-regulation of Nm23 by alcohol may promote RhoA activation through estrogen regulation to favor ITGA5-mediated breast cancer progression." (PMID 21838876, 2011). "Recently, clinical studies have revealed the correlation of increased expression of RhoA and invasion, metastasis and progression of several solid tumors including liver, bladder, esophageal, head and neck, ovary, gastric, testicular, lung and breast carcinomas." (PMID 20704716, 2010). "These signal transduction modes likely influence each other during the EMT, since RhoA is involved in TGFβ1-mediated AKT activation, as shown for breast cancer cells." (PMID 41388158, 2025). "PROCR is known to activate several signaling pathways in breast cancer cells, including ERK, PI3K–Akt–mTOR, and RhoA–ROCK–p38 pathways." (PMID 40631077, 2025). "Knockdown of both RhoA and RhoC GTPases by siRNA was reported to inhibit the proliferation and invasion of MDA-MB-231 breast cancer cells." (PMID 40214422, 2025).